MUSK (muscle associated receptor tyrosine kinase)
Diseases named in the same sentence as MUSK in open-access papers (continued):
Sharing a sentence is not in itself a finding about the gene and the disease.
myasthenia gravis (continued). "Myasthenia gravis (MG) is an autoimmune disease characterized by muscle weakness with fatigue and mediated by autoantibodies against acetylcholine receptor (AChR) or muscle-specific tyrosine kinase (MuSK)." (PMID 38664714, 2024). "Mutations in genes that govern the assembly and maintenance of neuromuscular synapses, or mediate synaptic transmission, are responsible for congenital myasthenia, whereas autoantibodies to key postsynaptic proteins, such as AChRs and MuSK, are responsible for autoimmune myasthenia gravis (MG)." (PMID 39288173, 2024). "In an experimental NMDAR AE model and a myasthenia gravis mouse model, NMDAR CAAR T cells and MuSK CAAR T cells were administered." (PMID 39276207, 2024). "Positive antibodies (Anti-AChR, Anti-MuSK, LRP4) and electromyography aid in diagnosis, and approximately 10% of myasthenia gravis patients can also have thymoma." (PMID 39624461, 2024). "However, a minority of patients have antibodies against muscle-specific tyrosine kinase (MuSK), which is referred to as MuSK myasthenia gravis (MuSK-MG)." (PMID 38975540, 2024). "MG: myasthenia gravis; AChRa: acetylcholine receptor; MUSK: muscle-specific kinase; MGFA: MG-Foundation of America; MG-CS: MG-Composite Scale; MG-ADL: MG-Activities of Daily Living; MG-QoL-15r: MG-Quality of Life-15-revised; QMG: Quantitative-MG; NA: not applicable." (PMID 39006634, 2024). "After initial examination of 70 patients for eligibility, two patients were not confirmed to be eligible in the first stage, due to misdiagnosis of ALS, one of them had myasthenia gravis (MG) with anti-MUSK antibodies and the second patient had SMA (Spinal muscular atrophy) type 4." (PMID 38464738, 2023). "Antibodies to MuSK identify a rare subtype of myasthenia gravis (MuSK-MG)." (PMID 35463138, 2022). "In comparison to previous reports that investigated treatment-refractory patients, our findings differ insofar as we could not find an association of thymoma-associated myasthenia gravis, presence of MuSK-antibody or female sex with treatment-refractory myasthenia gravis." (PMID 31828474, 2020). "The effect of the SHP2 inhibitor NSC-87877 on MuSK phosphorylation and AChR clustering was tested in C2C12 myotubes with 31 MuSK-myasthenia gravis (MG) sera and purified MuSK-MG IgG4 preparations." (PMID 31831571, 2020). "In addition, an MG cohort (both AChR autoantibody positive, n = 20, and MuSK autoantibody positive, n = 20) from the Yale Myasthenia Gravis Clinic was included for assay controls." (PMID 30824481, 2019). "Myasthenia gravis (MG) is an autoimmune disease of the neuromuscular junction with antibodies (abs) targeting the acetylcholine receptor (AChR) or the muscle-specific tyrosine kinase (MuSK), inducing muscle weakness and excessive fatigability." (PMID 29765992, 2018). "Myasthenia gravis (MG) is an organ-specific, autoimmune disorder, which is generally mediated by anti-acetylcholine receptor (AChR) or, less frequently, by anti-muscle-specific receptor tyrosine kinase (MuSK) antibodies (Ab) at the neuromuscular junction." (PMID 27623618, 2016). "MuSK antibody-positive myasthenia gravis (MuSK-MG) accounts for 5 to 15% of autoimmune MG." (PMID 26355076, 2015). "Anti-ganglioside antibodies (including anti-GQ1b) were negative, as were markers for myasthenia gravis (AChR, MuSK) and paraneoplastic syndromes (Hu, Ri, Yo, Ma2, CRMP5, Titin, Sox1, Zic4, Tr, Recoverin, VGCC antibodies) that formed part of our differential." (PMID 41356869, 2025). "Since IgG4 is not a good complement activator, the role of complement in MuSK antibody-positive myasthenia gravis patients is negligible." (PMID 40422242, 2025). "Overall, these structural differences between antibodies to AChR and MuSK explain why complement inhibitors do not seem to be effective in MuSK antibody-mediated myasthenia gravis, which is predominantly an IgG4-driven process." (PMID 40422242, 2025).
myasthenia gravis (continued). "Preclinical studies in a myasthenia gravis model with circulating anti-MuSK autoantibodies have shown that MuSK-CAAR T cells can reduce anti-MuSK antibody titers without inducing widespread B cell depletion." (PMID 40873568, 2025). "The absence of a decremental response on RNS testing, along with negative anti-acetylcholine receptor (anti-AChR) and anti-muscle-specific kinase (MuSK) antibody assays, effectively ruled out myasthenia gravis." (PMID 40656332, 2025). "Myasthenia gravis (MG) is defined as an autoimmune neuromuscular disorder where autoantibodies disrupt synaptic transmission at the neuromuscular junction by targeting the acetylcholine receptor (AChR), muscle-specific kinase (MuSK), or other proteins related to the AChR complex." (PMID 39479090, 2024). "Myasthenia gravis (MG) is an autoimmune disease, affecting the neuro-muscular junction, which is characterized by weakness of the skeletal muscles mediated by auto-antibodies, including acetylcholine receptor (AchR) antibodies, muscle-specific tyrosine kinase (MuSK) antibodies, etc.." (PMID 38297367, 2024). "Another multicenter analysis was performed on seronegative myasthenia crisis (SNMC), a life-threatening critical condition of myasthenia gravis without antibodies to either AChR or MuSK." (PMID 38881870, 2024). "Fifth, this study measured only the concentrations of AchR-Ab in all patients with MG but did not measure other myasthenia gravis-related antibodies, such as anti-MuSK antibodies, anti-LRP4 antibodies, anti-titin, and anti-RyR antibodies, in all the patients." (PMID 35265719, 2022). "Myasthenia gravis (MG) is an autoimmune neuromuscular disorder characterized by circulating autoantibodies against functionally important components of the postsynaptic membrane, including acetylcholine receptor (AChR) and muscle-specific tyrosine kinase (MuSK)." (PMID 35463138, 2022). "Myasthenia gravis (MG) is a chronic autoimmune disorder of the neuromuscular junction characterized by autoantibodies against acetylcholine receptors (AChR-Ab), muscle-specific kinase (MuSK-Ab), lipoprotein-related protein 4, or agrin in the postsynaptic membrane at the neuromuscular junction." (PMID 35645352, 2022). "The third group is called “double seronegative” myasthenia gravis and is without both AChR-Abs and anti-MuSK antibodies." (PMID 34439676, 2021). "Based on the mechanism of autoimmune disease and antibodies, invasive skeletal muscle molecules, thymus status, genetic characteristics, disease phenotype and response to treatment, myasthenia gravis is divided into early and late ocular subtypes (OMG), seronegative, thymoma, LRP4, MuSk." (PMID 34930325, 2021). "Myasthenia gravis (MG) is an autoimmune disease in which antibodies bind to acetylcholine receptors (AChR) or to other functional molecules, such as muscle-specific kinase (MuSK) and lipoprotein-receptor-related protein 4 (LRP4), in the postsynaptic membrane at the neuromuscular junction (NMJ)." (PMID 33633666, 2021). "Patients with autoimmune myasthenia gravis (MG) should be further classified before initiating therapy, as treatment response varies for ocular versus generalised, early onset versus late onset, and acetylcholine receptor antibody positive versus MuSK antibody positive disease." (PMID 22007295, 2011). "However, for myasthenia, clinical assessment and neurophysiological studies overrule the biomarkers (anticholinesterase (anti-ACR) and muscle-specific tyrosine kinase (anti-MUSK) antibodies) in comparison to non-ICI-induced myasthenia gravis." (PMID 41393647, 2025). "Patient demographics and clinical characteristics in our study were largely similar to those reported by the Japanese myasthenia gravis registry (JAMG-R), in which mean patient age was 60 years, 60% of patients were female, 44% were MGFA Class II, 82% were anti-AChR, and 3% were anti-MuSK positive." (PMID 41458125, 2025).
myasthenia gravis (continued). "For example, in the case of myasthenia gravis (MG), muscle‐specific kinase (MuSK) CAAR‐T cells are engineered to target and eliminate B cells that produce MuSK antibodies." (PMID 41208643, 2025). "The standard diagnosis of myasthenia gravis relies on the reliable demonstration of anti-AChR abs or anti-MuSK abs; however, these may not always be available." (PMID 25136468, 2014). "Myasthenia gravis (MG) was suspected, but serological testing for muscle-specific kinase (MuSK) and acetylcholine receptor (AChR) antibodies was negative." (PMID 41368047, 2025). "Antibody-negative myasthenia gravis refers to cases of MG in which AChR, MuSK, or LRP4 antibodies are undetectable." (PMID 40689326, 2025). "Myasthenia gravis can be divided according to the type of autoantibodies into AChR antibody-positive MG, MuSK antibody-positive MG, and a small percentage of MG with no detectable antibodies to either of these, which is called double-negative MG (DNMG)." (PMID 38881870, 2024). "Up to 50% of patients with myasthenia gravis (MG) without acetylcholine receptor antibodies (AChR-Abs) have antibodies to muscle-specific kinase (MuSK)." (PMID 37582613, 2023). "Thirty to fifty percent of patients with acetylcholine receptor (AChR) antibody (Ab)-negative myasthenia gravis (MG) have Abs to muscle specific kinase (MuSK) and are referred to as having MuSK-MG." (PMID 32457737, 2020). "Testing for antibodies against the acetylcholine receptor (AChR) and the muscle-specific kinase (MuSK) is useful to rule out myasthenia gravis (MG)." (PMID 29874875, 2018). "Myasthenia gravis (MG) is an autoimmune disease mediated by autoantibodies against molecules in the neuromuscular junction (NMJ), such as anti-acetylcholine receptor antibody (AChR-Ab) or anti-muscle-specific receptor tyrosine kinase antibody (MuSK-Ab)." (PMID 25192469, 2014). "Acetylcholine receptor (AChR), MuSK, and LRP4 antibodies were all negative, consistent with seronegative ICI-induced myasthenia gravis." (PMID 42261457, 2026). "The efficacy of efgartigimod in non-exacerbation MuSK-Ab-positive patients with MG has been demonstrated in a phase III clinical trial, with all three patients showing positive treatment outcomes as responders on the Myasthenia Gravis Activities of Daily Living (MG-ADL) scale." (PMID 39628891, 2024). "The results of RNS testing in myasthenia gravis patients with anti-MuSK antibodies are similar to those from SFEMG testing, showing a higher rate of positive results (sensitivity 86%) for facial muscle testing compared to MG cases with AchR antibodies (sensitivity 82%)." (PMID 38534400, 2024). "Initial concerns included myasthenia gravis and Miller-Fisher syndrome, but further investigations, including repetitive nerve stimulation (RNS), acetylcholine receptor (AChR), and muscle-specific kinase (MuSK) antibody testing, were negative." (PMID 40656332, 2025).
myasthenia (40 papers, 2011 to 2026). "Insights regarding the pathogenic mechanism by which MuSK antibodies cause myasthenia were provided by further in vitro experiments performed on cultured myotubes, which are derived from the mouse C2C12 immortalized muscle cell line." (PMID 32982689, 2020). "MuSk positive myasthenia are less commonly associated with thymoma or thymic hyperplasia and may show poor response to conventional therapy including thymectomy and pyridostigmine." (PMID 40656929, 2025). "Muscle-specific tyrosine kinase (MuSK) myasthenia can present with tongue weakness and atrophy, potentially being mistaken for bulbar ALS." (PMID 39337454, 2024). "All patients with MuSK Ab+ gMG treated with rozanolixizumab had Myasthenia Gravis Foundation of America Disease Class II or III at baseline." (PMID 39297052, 2024). "Most patients with myasthenia have autoantibodies targeted at acetylcholine receptors or, less commonly, muscle-specific kinase - MuSK." (PMID 35976295, 2022). "MuSK-Ab are increasingly investigated in AChR-Ab positive patients, who are treatment-resistant or develop clinical features less typical of AChR-myasthenia." (PMID 33923771, 2021). "Accordingly, the first step in a patient with the clinical features of myasthenia should be tested for AChR-Ab and MuSK-Ab." (PMID 33923771, 2021). "Bivalent MuSK antibodies induced subclinical signs of myasthenia, but the extent was antibody dependent." (PMID 33753489, 2021). "The onset of myasthenia (MG) gravis with anti-muscle-specific tyrosine kinase (MuSK) antibodies most commonly peaks in the fourth decade of life, and MG with MuSK antibodies (MuSK-MG) rarely coexists with a malignant tumor." (PMID 32532281, 2020). "In children, this includes not only autoimmune conditions such as anti-acetylcholine (Anti-ACh) receptor myasthenia and anti-Muscle specific kinase (MuSK) myasthenia, but also congenital myasthenic syndromes (CMS)." (PMID 29470437, 2018). "Thus interference by IgG4 antibodies of the LRP4-MuSK interaction will be one pathogenic mechanism of MuSK antibodies, but IgG1-3 MuSK antibodies will also contribute to the reduced AChR density and neuromuscular dysfunction in myasthenia patients with MuSK antibodies." (PMID 24244707, 2013). "Here we report a case of late-onset MuSK-antibodies-positive Myasthenia Gravis presenting with signs of cognitive impairment and parkinsonism in addition to bulbar involvement and external ophthalmoplegia." (PMID 21822490, 2011). "Myasthenia-specific antibodies (acetylcholine receptor (AChR), muscle-specific kinase (MuSK), low-density lipoprotein receptor (LRP4)) may be positive, indicating the presence of concurrent myasthenia, especially when ocular or bulbar symptoms are predominant." (PMID 38927526, 2024). "Recent studies have found strong associations of certain HLA alleles in diverse tissue-specific IgG4-mediated diseases, such as LGI1 encephalitis (DRB1*07:01–DQB1*02:02 haplotype), anti-MusK myasthenia (DR14-DQ5 haplotype), or anti-IgLON5 disease (DRB1*10:01-DQB1*05:01)." (PMID 29145880, 2017). "In addition to this, about 8% of myasthenia cases have muscle‐specific kinase (MuSK) antibodies." (PMID 36306401, 2022). "Consequently, ACh mediation of functional neuromuscular transmission may be in a delicate balance with ACh suppression of AChR clusters in myasthenias, where pathology alters MuSK, or functionally related proteins." (PMID 25438154, 2014). "Thus, injections of rabbit sera containing IgG antibodies targeting MuSK CRD induce behavioral and motor deficits typical of myasthenia-like symptoms." (PMID 40504622, 2025). "In an IgG4 passive transfer MuSK myasthenia model in NOD/SCID mice, MuSK agonists caused accelerated weight loss and no rescue of myasthenic features." (PMID 37156800, 2023). "Anti-MuSK-Ab was negative in our case, although it has been reported to be positive in drug-induced myasthenia." (PMID 36705187, 2022).
myasthenia (continued). "Although most of the patients with mutations in established CMS genes (such as DOK7, MUSK, RAPSYN, CHRNA1, CHRNB1, CHRND, and CHRNE) do not show cognitive symptoms, in some newly identified CMS subtypes, myasthenia is only one element of a more severe and complex clinical spectrum." (PMID 41575592, 2026). "None of the MuSK-immunized mice died of myasthenia-related symptoms." (PMID 25438154, 2014).
thymoma (39 papers, 2011 to 2025). A neoplasm arising from the epithelial cells of the thymus. "Other subtypes include thymoma-associated MG, anti-MuSK antibody-positive MG, ocular MG limited to periocular muscle involvement, and seronegative MG, in which neither AChR nor MuSK antibodies are detected." (PMID 41170262, 2025). "A retrospective study of 815 patients found severe MG at diagnosis, thymoma, and MuSK antibodies to be risk factors." (PMID 38321574, 2024). "It is also an open question which factors predispose patients to a refractory disease course with some observations suggesting an early onset, female gender, an association with thymoma or the presence of MuSK-antibodies as risk factors." (PMID 31828474, 2020). "The 208 patients included were classified as follow: 36 ocular MG, 40 EOMG, 72 LOMG, 25 thymoma-associated, 14 anti-MuSK and 21 double seronegative." (PMID 33324944, 2020). "Ideally, a valid biomarker in MG should easily differentiate MG patients from healthy individuals and also be able to differentiate MG subgroups, including EOMG versus LOMG, AChR+ versus MuSK+ MG, thymoma-associated MG, as well as OMG versus GMG." (PMID 32194544, 2020). "Age at onset of EOMG was significantly different when compared with thymoma-associated MG (28,9 ± 11,5 vs 45,0 ± 16,3 p = 0,000038), seronegative MG (28,9 ± 11,5 vs 48,2 ± 16,5 p < 0,00001) and anti-MuSK positive MG (28,9 ± 11,5 vs 44,8 ± 16,8 p = 0,00051)." (PMID 33324944, 2020). "It is thought that the patients who are seronegative for both antibodies, who do not have thymoma have a milder clinical picture, and those who are associated with thymoma, who have a late onset (>50 years) and who are anti-MuSK antibody positive have a more severe clinical picture." (PMID 37602241, 2023). "Risk factors for myasthenic crisis were thymoma, older age, MuSK antibodies, and previous crises." (PMID 37521306, 2023). "It will be of interest to determine whether endophenotypes, such as the identity of the autoantibody (AChR vs. MuSK vs. titin), the presence of thymoma or the occurrence of associated autoimmune diseases are associated with distinctive HLA-region signals." (PMID 25915571, 2015). "Fifty-two (64%) had very late-onset MG; 35% had a thymoma, and 72% had at least one comorbidity; seventy patients (86%) had antibodies against AChR, 7 (9%) against MuSK and 4 (5%) were seronegative." (PMID 40658304, 2025). "Significant differences were found among MGFA subtypes in relation to AChR (p < 0.001), MuSK (p < 0.001), titin (p < 0.001), disease complications (p < 0.001), thymoma (p < 0.001), and hypertension (p = 0.041)." (PMID 39968461, 2025). "Among MGFA subtypes, significant differences were detected in AChR, MuSK, titin, complications, thymoma, and hypertension." (PMID 39968461, 2025). "One patient with triple-SN MG had thymoma, and another with MuSK-Abs MG had thymic hyperplasia, but the prevalence of thymus disease was not different among the subgroups." (PMID 38316426, 2024). "Inconsistency can be explained by a wide spectrum of MG patients with varying disease severity, presence of thymoma, antibody status (anti-AChR antibodies or MuSK antibodies), and variation in autonomic assessment methods." (PMID 37755362, 2023). "MG with MuSK antibodies, thymoma MG, older age, and respiratory tract comorbidities all represent risk factors for insufficient ventilation and a severe generalized MG." (PMID 37101094, 2023). "The most frequent risk factors for refractory MG patients are young age, female gender, thymoma evidence, and MusK antibodies." (PMID 33728176, 2021). "A total of 83.8% were seropositive (including all with thymoma‐MG); in 6% of tested patients, anti‐MuSK antibodies were detected." (PMID 27781146, 2016). "The refractory MG patients are most commonly female with an early age of onset, anti-MuSK antibodies, and thymomas." (PMID 27790079, 2016).